PRL (prolactin)
Diseases named in the same sentence as PRL in open-access papers (continued):
Sharing a sentence is not in itself a finding about the gene and the disease.
Galactorrhea (127 papers, 2006 to 2026). Spontaneous flow of milk from the breast, unassociated with childbirth or nursing. "Healthcare professionals should be vigilant for ADEs like increased blood prolactin levels causing gynecomastia in males and galactorrhea in females when administering paliperidone palmitate." (PMID 39833706, 2025). "Although prolactinoma is a benign tumor, it can result in amenorrhea, galactorrhea, loss of libido, subfertility, osteoporosis, visual impairment, etc. due to the overproduction of prolactin (PRL) and the direct tumor mass effect." (PMID 38398117, 2024). "PRL-secreting PitNETs are more common in female patients and is often the cause of menstrual irregularities, galactorrhea, and infertility, while male patients lack symptoms such as dysmenorrhea or hypogonadism, making early-stage detection difficult." (PMID 38516477, 2024). "By the end of diestrus, a prolactin increase associated with a progressive reduction in P4 concentration can cause overt lactation and galactorrhea." (PMID 38539988, 2024). "Breast milk is considered as physiological nipple discharge and secondary galactorrhea is mostly related to elevating circulating PRL levels caused by various reasons, which can be regarded as functional nipple discharge." (PMID 36845388, 2023). "In another case of rechallenge, esomeprazole-induced galactorrhea was associated with elevated fasting prolactin levels of 276 ng/ml (5–25 ng/ml) and 656 pg/ml (20–145 pg/ml) estradiol after esomeprazole administration for 7 days." (PMID 35339194, 2022). "Shortly after the isolation of prolactin in the early 1970s, bromocriptine was found to inhibit prolactin secretion and began to be used in the treatment of galactorrhea and associated hypogonadism." (PMID 36013562, 2022). "Findings also showed that the main side effects caused by the increase in prolactin resulted in amenorrhea, galactorrhea, and gynecomastia." (PMID 34777053, 2021). "In turn, dysfunctions in the tuberoinfundibular pathway cause changes in prolactin secretion, which can cause galactorrhea and amenorrhea, as dopamine is responsible for inhibiting prolactin secretion." (PMID 32171543, 2020). "Due to the excessive production of prolactin, they mainly cause menstrual alterations and galactorrhea in women and decreased libido in men." (PMID 30542321, 2018). "The PRL-associated disturbances in gonadotropins and reproductive hormones exerted significant adverse effects on follicular growth and resulted in galactorrhea features in SPD-administered rats." (PMID 25083185, 2014). "Increased prolactin in patients receiving antipsychotics has been a concern most often because of loss of libido, amenorrhea, weight gain, galactorrhea, or even osteoporosis." (PMID 23533901, 2013). "The authors report that prolactin related effects were profoundly associated with increased suicide risk: amenorrhea increased the suicide risk by 64%, galactorrhea by 163% and gynecomastia by 200%." (PMID 23968123, 2013). "Atypical antipsychotics cause less prolactin elevation and/or galactorrhoea than typical antipsychotics." (PMID 17650327, 2007). "The cause of galactorrhea can vary as it may result from a pathological process in any of the different steps of the physiological axis of prolactin secretion." (PMID 41278565, 2025). "Normally, dopamine functions as an inhibitor to prolactin release; therefore, elevated serum prolactin levels may raise suspicion of dopamine deficiency, especially if associated with galactorrhea." (PMID 40291937, 2025). "In 2011, the Canadian Alliance for Monitoring Effectiveness and Safety of Antipsychotics in Children published a report on the association between elevated prolactin levels and adverse events such as gynecomastia, galactorrhea, menstrual irregularities, sexual dysfunction, and decreased libido." (PMID 27825323, 2016).
Galactorrhea (continued). "Raises in prolactin (PRL) levels may cause gynecomastia, galactorrhea, irregular menses, and amenorrhea in women, sexual dysfunction (decreased sexual desire, erectile-ejaculatory dysfunction, orgasmic dysfunction, vaginal dryness), and reduced fertility." (PMID 27209326, 2016). "Moreover, the PRL-associated abnormalities in gonadotropins and reproductive hormones exerted a significant effect on galactorrhea features and thickness of the epithelium, myomterium and endometrium of the uterus in CPZ-administrated rats." (PMID 26239213, 2015). "They discussed that elevated levels of prolactin may be associated with adverse events such as gynecomastia, galactorrhea, infertility, menstrual irregularities, oligomenorrhea, amenorrhea, sexual dysfunction, decreased libido, acne, and hirsutism in females." (PMID 25312992, 2014). "An increase in prolactin levels can cause amenorrhea, galactorrhea and other sexual disturbances." (PMID 23206324, 2012). "Since PRL is mandatory for milk production, aberrent physiology may be assumed as the cause of galactorrhea." (PMID 23675050, 2007). "Quetiapine causes less prolactin elevation and/or galactorrhoea than other atypical antipsychotics." (PMID 17650327, 2007). "Quetiapine, an atypical antipsychotic, may cause galactorrhoea due to prolactin level elevation." (PMID 17650327, 2007). "(2021) reported on the incidence of galactorrhea due to elevated prolactin levels during antipsychotic treatment, identifying significant sex‐ and age‐related differences within the AMSP cohort." (PMID 40817421, 2025). "In our opinion, PRL testing should be considered in patients with menstrual irregularities, galactorrhea, headaches or visual disturbances or in men with gynecomastia or hypogonadism." (PMID 41010681, 2025). "At age 26, because of oligomenorrhea, galactorrhea, headaches, and dizziness, she was diagnosed at another hospital with a centimetric pituitary prolactinoma (prolactin at diagnosis 82.9 μg/L (5.0–23.0 μg/L))." (PMID 41201503, 2025). "Because antipsychotic-induced galactorrhea results from systemic prolactin elevation, it is almost always bilateral; thus, a unilateral presentation is exceptionally rare and should prompt heightened concern for an underlying pathological process." (PMID 41561265, 2025). "First, the clinical manifestation that led to medical attention was a trivially elevated prolactin which resulted in galactorrhea." (PMID 40642336, 2025). "A 20-year-old female individual, previously healthy, was referred for investigation of galactorrhea and a prolactin level of 31 ng/mL (<20 ng/mL) (SI: 31 μg/L, <20 μg/L)." (PMID 40642336, 2025). "Dysfunctional secretion of prolactin can precipitate galactorrhea which manifests as milky discharge from the nipple unrelated to the physiological milk production in pregnant or breastfeeding women." (PMID 40271284, 2025). "Some patients exhibited mildly elevated serum prolactin levels due to compression of the pituitary stalk, leading to galactorrhea and amenorrhea." (PMID 40598734, 2025). "The iatrogenic galactorrhea with normal prolactin levels appears to be due to indirect inhibition of tuberoinfundibular dopaminergic neurons." (PMID 39006722, 2024). "Serum levels of prolactin above the reference range for sex and age were reported in 7 patients (13.7%), with the occurrence of galactorrhea in one case during anti-seizure therapy." (PMID 38540345, 2024). "The symptoms of high prolactin (acne, hirsutism) affect women’s quality of life and amenorrhea, breast swelling and galactorrhea induce delusions of pregnancy." (PMID 39120186, 2024). "Galactorrhoea and amenorrhoea were relatively common in females with prolactin-secreting tumours, with a higher incidence of oligo-amenorrhoea in macro-tumours, in agreement with previous studies." (PMID 36001286, 2023).
Galactorrhea (continued). "The clinical manifestations of patients experiencing preoperative menstrual disorders, galactorrhea, or sexual dysfunction weren’t entirely elucidated by preoperative gonadal function and serum prolactin levels." (PMID 37964947, 2023). "In typical cases, female patients exhibit galactorrhea and amenorrhea due to serum prolactin (PRL) elevation, and during pregnancy, they should be carefully treated." (PMID 35892862, 2022). "Less commonly (0.1–1%) reported side effects are akathisia and symptoms that are a consequence of elevated prolactin levels, such as gynecomastia, galactorrhea, and weight increase." (PMID 35455705, 2022). "Two weeks after stopping omeprazole, serum PRL levels returned to normal (18.8 ng/mL), accompanied by resolution of galactorrhea." (PMID 35339194, 2022). "Prolactin was not isolated in humans until the early 1970s, when Kleinberg and Frantz developed a bioassay that was able to quantify elevations in prolactin among breastfeeding women and patients with galactorrhea." (PMID 36013562, 2022). "Upon discontinuing esomeprazole for 3 days, galactorrhea was resolved, and PRL levels declined to 23 ng/ml." (PMID 35339194, 2022). "In typical cases, female patients exhibit galactorrhea and amenorrhea due to serum prolactin (PRL) elevation, and patients during pregnancy should be carefully treated." (PMID 35892862, 2022). "Clinicians should be aware of the possible occurrence of galactorrhea under treatment with quetiapine, especially when combined with another prolactin-raising drug." (PMID 33768297, 2021). "Estimates of the prevalence of galactorrhea in cases of elevated prolactin levels vary from 10 to 50%." (PMID 33768297, 2021). "Serum prolactin levels were documented in 123 (72.4%) of the 170 galactorrhea cases, the reference value was set to 15 ng/ml." (PMID 33768297, 2021). "They reported that plasma prolactin levels increased by 100% 2–8 h after a single dose (3 mg) of alprazolam, further reporting a case of galactorrhea under alprazolam in monotherapy in very high dosage (9 mg per day)." (PMID 33768297, 2021). "High prolactin disrupts menstrual cycles, diminishes fertility and leads to galactorrhea, amenorrhea, hirsutism and acne." (PMID 32756418, 2020). "Consequences of having high prolactin levels include galactorrhea and gynecomastia in female and male patients, respectively." (PMID 33343407, 2020). "There were 30.95% patients who had gynaecomastia or galactorrhea, and 8.68% patients who had increased serum prolactin level." (PMID 31293587, 2019). "Although her serum prolactin level dropped to 1.7 ng/mL and her galactorrhea was resolved, she continued to complain of headaches and nausea." (PMID 31731892, 2019). "The tyrosine releasing hormone can enhance release of prolactin which can contribute to galactorrhea, the milky discharge from the nipple." (PMID 30167396, 2018). "After 15 months of using cabergoline and 43 weeks after starting the treatment, the concentration of prolactin was 103 ng/mL, and the patient reported regular menstrual cycles, improved libido, and the disappearance of galactorrhea." (PMID 30542321, 2018). "During the follow-up, she still presented menstrual irregularities and galactorrhea, and prolactin concentration remained elevated." (PMID 30542321, 2018). "One of these cases with high prolactin levels (>20 ng/mL) had headache, menstrual irregularity and galactorrhea, the other one had only headache." (PMID 28418336, 2017). "Elevated prolactin levels lead to galactorrhea or lactation, the persistence of corpus luteum, and suppression of Follicle-stimulating hormone and LH secretion, ultimately resulting in amenorrhea." (PMID 29662961, 2017). "Although the patient was started on cabergoline for management of galactorrhea prior to the diagnosis of allergic fungal sinusitis, surgical removal of fungal material was critical in normalizing prolactin levels." (PMID 26998375, 2016).
Galactorrhea (continued). "The effect of prolactin on gynecomastia in men and galactorrhea in women has also been reported elsewhere." (PMID 27825323, 2016). "In a study of patients treated biweekly with 25–50 mg of risperidone for 24 weeks, 5 cases (16 %) of prolactin-related adverse events, comprising 2 cases (6.5 %) of gynecomastia/galactorrhea and 3 cases (9.7 %) of amenorrhea/dysmenorrhea, were reported." (PMID 27825323, 2016). "Three RCTs reported overall prolactin-related adverse events, gynecomastia/galactorrhea, and amenorrhea/dysmenorrhea in patients treated with varying doses of aripiprazole and risperidone." (PMID 27825323, 2016). "In this patient, the mass effect on the infundibulum was responsible for blocking the inhibitory tuberoinfundibular dopamine pathway, resulting in uninhibited pituitary prolactin release and manifesting as galactorrhea." (PMID 26998375, 2016). "The antipsychotic amisulpride predominantly produced endocrine events (galactorrhea, libido reduction, increased prolactin) and weight gain compared to other agents." (PMID 27187783, 2016). "While the focus was efficacy outcomes, prolactin-related and sexual side effects (amenorrhea, oligomenorrhea, erectile dysfunction, decreased libido, hirsutism, breast symptoms, galactorrhea, prolactin levels) were combined and analyzed together." (PMID 25312992, 2014). "Outcome measures include resolution of menstrual abnormalities or galactorrhea, improvement in sexual functioning, prolactin level improvement, changes in bone resorption measures, psychiatric symptoms, quality of life and related metabolic effects." (PMID 23968123, 2013). "The phenomenon was particularly marked for prolactin-related adverse events, namely amenorrhea (+64%), galactorrhea (+163%) and gynecomastia (+200%)." (PMID 22812421, 2012). "The following case report highlights an interesting observation of paroxetine-induced galactorrhoea at therapeutic dosage and serum prolactin values of this patient comes out to be normal." (PMID 21206628, 2010). "Escitalopram was discontinued with resolution of the patient's galactorrhea and normalization of her prolactin level." (PMID 20046401, 2009). "A 36-year-old woman developed galactorrhea after initiation of escitalopram for depression and was found to have an elevated prolactin level." (PMID 20046401, 2009). "The patient's serum prolactin level (7.5 ug/ml) was within normal limits and was measured on a single sample at the time that the patient's galactorrhea was resolving." (PMID 19852783, 2009). "I investigated a number of other potential reasons for elevation of prolactin and consequent galactorrhoea." (PMID 17650327, 2007). "Prolactin levels in these patients were normal, and in all subjects, the galactorrhea resolved spontaneously within the next year in both patients who continued use and those who discontinued use of DMPA." (PMID 16680366, 2006). "However, high estrogen levels inhibit the effects of prolactin on mammary glands suggesting galactorrhea will only present with moderate inhibition of estrogen metabolism." (PMID 40271284, 2025). "One of the first clinical reports on this issue described ‘’galactorrhoea-endometriosis syndrome” in nine patients with endometriosis: eight had galactorrhoea either at diagnosis or after treatment with danazol, moreover, in seven of them, the prolactin serum concentrations were normal." (PMID 39407928, 2024). "Although menstrual disturbances, gynecomastia, and galactorrhea are not included in sexual dysfunctions, they were assessed in this study because of their association with serum prolactin levels." (PMID 37720899, 2023). "In those years, the ability of thyrotropin-releasing hormone (TRH) to stimulate the release of prolactin (PRL) in addition to TSH was also recognized, thus explaining the presence of high serum levels of PRL and the occurrence of galactorrhea in hypothyroid patients." (PMID 35207645, 2022).
Galactorrhea (continued). "The level of PRL is usually raised with symptoms of galactorrhea." (PMID 35339194, 2022). "In our sample, we found 5 cases (2.9%) of galactorrhea in spite of normal levels of prolactin." (PMID 33768297, 2021). "The prolactin level was 103.3 ng/ml 1 day after galactorrhea had started (ref. < 15 ng/ml)." (PMID 33768297, 2021). "Abnormally high serum prolactin levels leading to galactorrhea may be the result of such an accumulation." (PMID 32566351, 2020). "To examine this proposal, we recruited two women with lactotrope microadenomas that were resistant to cabergoline therapy and who had chronically elevated PRL levels and secondary amenorrhea with galactorrhea, reduced or inappropriately normal gonadotropins, and low E2 levels." (PMID 29264460, 2017). "After cabergoline treatment was started, prolactin levels normalized and galactorrhea disappeared." (PMID 28791188, 2017). "Prolactinomas, which comprised the majority of cases (10/17), may present with gynecomastia, erectile dysfunction, decreased libido, galactorrhea, amenorrhea (in females), and an elevated prolactin level." (PMID 26885420, 2016). "MedDRA-preferred terms that were considered potentially prolactin-related AEs were amenorrhea (RLAT: 1.8%), erectile dysfunction (Flu-Dec: 2.3%), galactorrhea (Fpt-Dec: 2.9%; Flu-Dec: 2.3%), loss of libido (Zuc-Dec: 2.4%) and sexual dysfunction (Hal-Dec: 1.9%; RLAT: 1.8%)." (PMID 25999398, 2015). "In the present case, the appearance of some typical signs such as amenorrhea, galactor rhea and growth of the face, tongue and extremities (resulting from increased GH and prolactin levels) contributed towards the inves tigation and aided in making the diagnosis." (PMID 25351760, 2014). "Direct effects of elevated prolactin on breast tissue may lead to galactorrhea in women and gynecomastia in men." (PMID 25312992, 2014). "Prolactin elevation and consequent galactorrhoea is a known side effect of antipsychotics." (PMID 17650327, 2007). "Ms AB had galactorrhoea and raised prolactin levels at only 100 mg of quetiapine daily." (PMID 17650327, 2007). "Yet, there have been some reports of its adverse effect on the prolactin-galactorrhoea mechanism." (PMID 17650327, 2007). "When monitoring is suboptimal, this could cause severe risks, as abnormalities in blood glucose and a high body weight could result in the development of diabetes mellitus, and abnormalities in blood prolactin levels could lead to gynecomastia and galactorrhea." (PMID 33716833, 2021). "A substantial number of studies have demonstrated that the treatment of schizophrenia with risperidone may cause a substantial plasma prolactin increase and an unacceptably high incidence of prolactin related symptoms (PRS), such as amenorrhea, galactorrhea, gynecomastia, and sexual dysfunction." (PMID 27829454, 2016). "Physiologically, prolactin-related galactorrhea is generally bilateral and non-spontaneous and therefore does not exclude malignancy when symptoms are asymmetric." (PMID 41561265, 2025). "If, after 6 months of thyroxine therapy, TSH levels decline but PRL levels remain elevated, accompanied by persistent amenorrhea, galactorrhea, and no reduction in pituitary size, a pituitary PRL adenoma should be suspected." (PMID 40893882, 2025). "In this, and a prior study of LB-102, there were no clinically observable effects of prolactin elevation (for example: galactorrhea or menstrual irregularities)." (PMID 39414986, 2024). "Occasionally galactorrhea occurs in non-lactating women with regular menses and normal PRL values (‘nonpuerperal idiopathic galactorrhea’)." (PMID 35000899, 2022). "The medication was switched to risperidone 4 mg/d in monotherapy, under which galactorrhea did not re-appear despite further increases in prolactin levels." (PMID 33768297, 2021). "It is worth commenting that some women present with non-puerperal galactorrhea in the presence of regular menstrual cycles and normal PRL levels." (PMID 29768629, 2018).